RB1 (RB transcriptional corepressor 1)
Diseases named in the same sentence as RB1 in open-access papers (continued):
Sharing a sentence is not in itself a finding about the gene and the disease.
osteosarcoma (212 papers, 2000 to 2026). A usually aggressive malignant bone-forming mesenchymal neoplasm, predominantly affecting adolescents and young adults. "A mutation in RB1 and its relatives significantly increases the risk of developing osteosarcoma, as it interferes with the cell’s ability to control the cell cycle, leading to unchecked cellular proliferation." (PMID 40507962, 2025). "Preclinical evaluation of PARP inhibitors have also shown promise in multiple RB1-deficient cancers such as lung adenocarcinoma and osteosarcoma." (PMID 40826136, 2025). "TSC2 and RB1 genes have been found to be mutated in acute T-cell lymphoid leukemia and osteosarcoma." (PMID 38672648, 2024). "Loss of function of the Retinoblastoma gene (RB1) due to mutations is commonly seen in human osteosarcomas." (PMID 38248470, 2024). "A meta-analysis that included 491 patients with osteosarcoma showed that RB1 mutations were associated with a significantly reduced histological response to chemotherapy and a high risk of metastasis in osteosarcoma." (PMID 39654890, 2024). "In the present study we found that RB1 mutation was detected in all samples, and RB1 protein was downregulated in osteosarcoma tissue and cryopreserved PDCs." (PMID 38744935, 2024). "To understand molecular changes in osteosarcoma, we have attempted to create a deficiency of Rb1 in osteoblasts and study how it affects normal growth and differentiation." (PMID 38248470, 2024). "Osteosarcomas have a higher prevalence of RB1 gene mutations and are consistently high-grade and poorly differentiated, with many showing detectable metastasis." (PMID 38248470, 2024). "The loss of function or gene deletion of the retinoblastoma (RB1) gene is an major cause of osteosarcoma, and RB1 lacks inducible mitochondrial oxidative phosphorylation." (PMID 38586328, 2024). "The results of the RB1 mutation of osteosarcoma tissue and cryopreserved PDC were confirmed in a Sanger sequencing experiment, as was the low expression of RB1 protein in a western blotting." (PMID 38744935, 2024).
osteosarcoma (continued). "RB1 is a well-established tumor suppressor gene reported to be mutated in multiple malignant tumor types including osteosarcoma." (PMID 37197432, 2023). "In patients with germline RB1 mutations, the incidence of osteosarcoma increases up to 500 times that of the general population." (PMID 37894411, 2023). "On the other hand, in children, we have retinoblastoma syndrome, with mutations in the Rb1 gene, in which up to 7% of carrier patients are predisposed to develop osteosarcoma." (PMID 36499267, 2022). "Loss-of-function mutations at the retinoblastoma (RB1) gene are associated with increased mortality, metastasis, and poor therapeutic outcome in several cancers, including osteosarcoma." (PMID 36068209, 2022). "The association between mutations in the Retinoblastoma 1 (RB1) gene and predisposition to osteosarcoma are well known." (PMID 35887382, 2022). "Uhrf1 loss drastically delayed tumor onset, decreased pulmonary metastasis, and increased the lifespan of developmental osteosarcoma mouse models carrying Rb1 mutation." (PMID 36068209, 2022). "RB1 genetic alterations are associated with increased mortality, metastasis, and poor response to chemotherapy in osteosarcoma." (PMID 36068209, 2022). "Another meta‐analysis has shown that loss of RB1 function leads to a 1.6 two‐fold increase in the mortality of patients with osteosarcoma, a significant increase in osteosarcoma metastasis, and a notable decrease in osteosarcoma response to chemotherapy." (PMID 34799997, 2022). "Biallelic mutations targeting RB1 are prominently associated with difficult to treat cancers, including osteosarcoma." (PMID 34862364, 2021). "To investigate if selective PARPi sensitivity in RB1-mutant osteosarcomas is a consequence of RB1 loss, we depleted RB1 in RB1-normal osteosarcoma lines CAL72 or 143b using multiple RB1-targeting small-hairpin RNAs (shRNA)." (PMID 34862364, 2021). "Loss-of-function mutations in the RB1 tumour suppressor are key drivers in cancer, including osteosarcoma." (PMID 34862364, 2021). "The frequency of osteosarcoma in individuals with mutations in the RB1 gene is higher than that in the population." (PMID 34646831, 2021).
osteosarcoma (continued). "Germline loss of function RB1 gene mutations are known to be causative in Rb and are associated with increased risk of osteosarcoma development." (PMID 33375764, 2020). "Another well-characterized gene implicated in osteosarcoma is RB1, localized to chromosome 13q14 and encoding the 110 kDa pRB1 protein that negatively regulates cell cycle progression." (PMID 30622235, 2019). "In particular, the loss of RB1 occurs in angiosarcomas and osteosarcomas, supporting a role for tumor suppressor in pathogenesis." (PMID 30598078, 2018). "Loss of function mutations at the RB1 gene are associated with increased mortality, metastasis and poor therapeutic outcome in osteosarcoma." (PMID 30220967, 2018). "In this study, we examined the transcription factor E2F family members that are associated with increased malignancy in Rb1-null osteosarcoma tumors." (PMID 30220967, 2018). "Of the four osteosarcoma cell lines used in this study, SaOS-2 is the only one bearing an RB1 mutation." (PMID 30220967, 2018). "Specifically, loss of RB1 function is associated with increased risk of osteosarcoma metastasis and poor response to chemotherapy, compared with osteosarcoma patients with intact RB1." (PMID 30220967, 2018). "Loss-of-function mutations of the RB1 gene in osteosarcoma are associated with poor therapeutic outcome, as defined by increased mortality, metastasis, and poor response to chemotherapy." (PMID 30220967, 2018). "Genetic alterations of the retinoblastoma susceptibility (RB1) gene have been implicated in the development and progression of osteosarcoma." (PMID 29056713, 2016). "Children with hereditary retinoblastoma, a condition in which tumors arise from biallelic functional loss of RB1, have a 1,000 fold increased risk of osteosarcoma compared to the general population." (PMID 27074562, 2016). "RB1 has epigenetic functions, which have not been well sorted out in osteosarcoma but previous publications have reported on the significant role of RB-loss in osteosarcoma." (PMID 26802029, 2016). "Although the Rb1 gene is also frequently mutated in human osteosarcoma, previous studies indicated that Rb1 deletion in osteoblast precursors only has modest effects and does not promote OS." (PMID 26317218, 2015). "RB1 inactivating mutations with consequent loss of Rb expression are observed in over 70% of sporadic osteosarcomas, and Rb loss has been shown to abrogate osteoblast differentiation." (PMID 26555075, 2015).
osteosarcoma (continued). "This is the first experimental demonstration of a functional and genetic link between reduced Rb1 expression from a common promoter variant and increased risk for osteosarcoma after radiation exposure in mice." (PMID 25092376, 2014). "Somatic mutations of RB1 are found in 30–75% of osteosarcoma specimens depending on the testing techniques utilized and the population studied." (PMID 22550413, 2012). "One 2003 study from Spain suggested that osteosarcoma patients with loss of heterozygosity of RB1 had worse prognosis." (PMID 22550413, 2012). "Inactivation of RB1, located at chromosome 13q14.2, is frequent in sporadic osteosarcoma, and when it occurs due to germline mutation, osteosarcoma incidence significantly increases." (PMID 22685381, 2012). "RB1 gene mutations are present in 70% of all pediatric osteosarcoma patients." (PMID 38248470, 2024). "RB1 mutation in osteosarcoma is responsible for tumor carcinogenesis and progression." (PMID 37197432, 2023). "Moreover, RB1 mutation has been verified to induce PARPi hypersensitivity in osteosarcoma tumor cells." (PMID 37937640, 2023). "This suggests that UHRF1 upregulation may contribute to tumor progression following RB1 loss in osteosarcoma." (PMID 36068209, 2022). "Novel osteosarcoma genetically engineered mouse models confirmed that knocking out Uhrf1 considerably decreased metastasis and reversed the poorer survival associated with Rb1 loss." (PMID 36068209, 2022).
osteosarcoma (continued). "Moreover, the incidence of osteosarcoma is increased 500-fold in patients with a pRb deficiency caused by mutation in the RB1 gene." (PMID 34717687, 2021). "Similarly, retinoblastoma is characterized by mutations to RB1, the retinoblastoma tumor suppressor gene, which has been identified as a driver in a subset of osteosarcoma." (PMID 33809018, 2021). "Loss of RB1 gene function has also been found to be associated with increased risk of osteosarcoma metastasis and a poor histological response to chemotherapy as compared with osteosarcoma patients with intact RB1 function." (PMID 33375764, 2020). "Mutations of the RB1 gene result in its dissociation from E2F and subsequent transcription of multiple genes involved in cell cycle progression, leading to malignant transformation and the progression of osteosarcoma." (PMID 33375764, 2020). "In addition to germline mutations, somatic mutations in RB1 were identified in 29–47% of osteosarcomas." (PMID 31741049, 2020). "In addition, Ginsenosides including compound K, Rb1, and Rc enhanced the cytotoxicity of Timo AIII in MG63 human osteosarcoma cells, in which Rb1 and Rc increased the population of apoptosis cell caused by Timo AIII." (PMID 32581782, 2020). "RB1 mutations are detected in between 10 and 60% of osteosarcoma tumors analyzed by NGS11–13." (PMID 33294214, 2020). "In hereditary retinoblastoma, an uncommon disorder where people have germline mutations of the retinoblastoma (RB1) gene, affected individuals have a reported 69-fold increase in the risk of osteosarcoma, which then increases to greater than 400-fold after radiation therapy." (PMID 31130627, 2019). "Furthermore, multiple studies have shown that RB1 loss is correlated with poor prognosis for patients with osteosarcoma." (PMID 30220967, 2018). "RB1 mutations are present in up to 70% of osteosarcoma cases." (PMID 30220967, 2018). "In previous studies, 25-35 % of osteosarcomas showed mutations or rearrangements of RB1." (PMID 26672768, 2016).